TRPV1 (transient receptor potential cation channel subfamily V member 1)
Diseases named in the same sentence as TRPV1 in open-access papers (continued):
Sharing a sentence is not in itself a finding about the gene and the disease.
melanoma (continued). "For instance, TRPV1 expression is significantly decreased in melanoma tissues and is inversely related to patient survival." (PMID 32575381, 2020). "Hereby, activation of TRPV1 expression or function inhibits in vitro and in vivo proliferation of melanoma cells." (PMID 32575381, 2020). "We show here that crosstalk between members of this receptor triad affects Ca2+ signaling responses induced by VEGFR transactivation of TRPV1 in UM 92.1 melanoma cells." (PMID 30483120, 2018). "We compare here the effects of TRPM8 activation on VEGF-induced transactivation of TRPV1 in an UM cell line (92.1) with those in normal primary porcine melanocytes (PM) since TRPM8 is upregulated in melanoma." (PMID 30483120, 2018). "Indeed, our results show that Xenopus melanophores express multiple and similar TRP channels, including Trpm8,15 Trpa1, Trpv1, Trpv2, and Trpv4, to those detected in mammalian melanocytes and melanoma cells." (PMID 40978134, 2025). "Regarding TRPV1, its stimulation suppresses melanoma and colon cancer growth." (PMID 38612571, 2024). "For example, TRPV1 antagonist creams may be applied to suspicious melanocytic lesions to prevent the development of tumorigenic melanoma." (PMID 37371563, 2023). "Altered expression patterns and functional changes in TRPM1, TRPM7, TRPM8, TRPV1, and TRPV4 have notably been found to modulate cell survival, apoptosis, proliferation, and migration in melanoma models." (PMID 40869148, 2025). "By analyzing our previously published datasets in silico, we discovered that naïve DRG neurons co-cultured with B16F10-mCherry-OVA melanoma cells and OVA-specific CD8+ T-cells exhibited elevated Oprl1 expression in cancer-exposed TRPV1+ neurons." (PMID 40951290, 2025). "Among the oncogenic TRP isoforms, TRPM7, TRPV1, TRPV4, and TRPM8 have received considerable attention due to their frequent overexpression in melanoma cells and their functional contributions to the malignant phenotype." (PMID 40869148, 2025). "In the context of melanoma, several TRP channel subtypes, including TRPM1, TRPM7, TRPV1, and TRPV4, have been shown to be differentially expressed and functionally active in tumor cells." (PMID 40869148, 2025). "According to these findings, TRPV1 expression may have a prognostic value; it has been proven that TRPV1 have a positive correlation with the presence of immune-stimulatory cells, rather than immunosuppressive ones, in several cancer types including oral, ovarian cancer, and melanoma." (PMID 39940997, 2025). "This review highlights the physiological expression of key TRP subfamilies (TRPM1, TRPM7, TRPM8, TRPV1, TRPV4, and TRPM2) in melanocytes and discusses their dysregulation in melanoma cells." (PMID 40869148, 2025). "In malignant melanoma, activation of TRPM8 blocks the activation of vascular endothelial growth factor (VEGF) on TRPV1, thus inhibiting VEGF-induced neovascularization and melanoma growth." (PMID 38892000, 2024). "In this study, we investigated the expression profiles of ASIC1, ASIC2, TRPV1 and TRPV4 in malignant melanoma (MM), squamous cell carcinoma (SCC), basal cell carcinoma (BCC) and in nevus cell nevi (NCN)." (PMID 34199609, 2021). "AEA is the CB1/CB2 receptor agonist, TRPV1 agonist, putative GPR55 agonist, induced in the A375 melanoma cell line a concentration-dependent cytotoxicity and decrease in cells viability." (PMID 34264513, 2021). "TRPM2, TRPM8, TRPV1, and TRPV2 have been identified in melanoma cell lines, where their expression and function confer susceptibility to apoptosis and necrosis." (PMID 34831352, 2021). "Multiple studies report that melanoma expresses CB1 and CB2 receptors, and other receptors like GPR family or TRPV1." (PMID 34264513, 2021).
melanoma (continued). "In this study, we investigate the expressions of ASIC1, ASIC2, TRPV1 and TRPV4 in squamous cell carcinoma (SCC), basal cell carcinoma (BCC), malignant melanoma (MM) and in nevus cell nevi (NCN)." (PMID 34199609, 2021). "In functional studies, 100–150 μM β-caryophyllene was found to inhibit spontaneous melanogenesis of mouse B16 melanoma cells, whereas 5 μM AEA was shown to induce apoptosis of primary human melanocytes most likely by activating TRPV1." (PMID 30845666, 2019). "In the present study, six thermo-TRPs including four heat sensors of TRPV1/2/3/4 and two cold sensors of TRPA1 and TRPM8 have been investigated among human melanocytes and melanoma cells." (PMID 30881453, 2019). "In the present study, six thermo-TRPs including TRPV1/2/3/4, TRPA1, and TRPM8 were examined in human primary melanocytes and melanoma cells." (PMID 30881453, 2019). "In a recent study, VAL inhibited skin photoaging-related ion channels, TRPV1 and ORAI1, and UV-induced melanogenesis in melanoma cells." (PMID 27630735, 2016). "These compounds are selective antagonists of the CB1, TRPV1, PPARα, PPARγ and GPR55 receptors respectively, the mRNA of which were found in B16 melanoma cells." (PMID 22429826, 2012). "Since melanoma is a genetically highly heterogenous disease, we were interested if CNR1, PPARα and TRPV1 are frequently mutated and therefore not accessible for inhibitory therapy." (PMID 37237519, 2023). "RNA sequencing of samples from B16F10-bearing mice revealed that malignant and melanoma-infiltrating immune cells had no detectable levels of neuronal markers (Nav1.8 or Trpv1), indicating that the NaV1.8 signal could be ascribed to tumour-infiltrating nerves." (PMID 36323780, 2022). "When assessing the effects of the eCBs, AEA was found to by cytotoxic (IC50: 5.87 ± 0.7 μM) in human A375 melanoma cells in a CB1-, COX2-, and a caspase-dependent manner, but neither CB2, nor TRPV1 antagonists influenced the effect." (PMID 30845666, 2019). "Meanwhile, 2-APB, an activator of TRPV2 (also activates TRPV1 and TRPV3 but does not affect TRPV4), clearly attenuated the proliferation of A2058 melanoma cells (IC50 = 150 μM)." (PMID 30881453, 2019).
prostate carcinoma (29 papers, 2012 to 2026). A carcinoma that arises from epithelial cells of the prostate gland. "Collectively, our results reveal that TRPV1 is not only overexpressed in PCa but also contributes to proliferation regulation and stemness features, positioning it as a potential diagnostic and prognostic biomarker for prostate cancer." (PMID 41694593, 2026). "However, the in vivo agonistic effect of CPZ may be also evaluated on the view of the ability of the TRPV1 antagonists themselves to cause hyperthermia and consequently cell death in prostate cancer cells." (PMID 22523714, 2012). "The transient receptor potential vanilloid 1 (TRPV1), the canonical capsaicin (CAP) receptor, has been implicated across diverse pathologies, yet its role in prostate cancer (PCa) remains elusive." (PMID 41694593, 2026). "In prostate cancer cells, capsaicin exerts anti-proliferative and pro-apoptotic effects through both TRPV1-dependent and -independent pathways." (PMID 41465505, 2025). "TRPV1 expression correlates with the tumor grade of prostate cancer and increases progressively with Gleason grade." (PMID 38734935, 2024). "Clinical studies suggest that TRPV1 expression is significantly greater in prostate cancer tissues than in healthy tissues." (PMID 38734935, 2024). "The TRPV1 agonist capsaicin promotes prostate cancer cell death by phosphorylating LKB1 and activating AMPK, whereas siTRPV1 inhibits LKB1 and AMPK phosphorylation." (PMID 38734935, 2024). "Our results from this study show that capsaicin activates AMPK in prostate cancer cells via a TRPV1/LKB1-dependent phosphorylation at Thr172." (PMID 35214061, 2022). "This shows that TRPV1 is required for LKB1 activation and that LKB1 is required for AMPK activation, highlighting a TRPV1/LKB1/AMPK signaling pathway in prostate cancer cells." (PMID 35214061, 2022). "Capsaicin effectively activates the transient receptor potential vanilloid 1 (TRPV1), a cation channel expressed in sensitive neurons as well as in other tissues, including the prostate and prostate cancer cells." (PMID 35214061, 2022). "In androgen-responsive NCaP prostate cancer cells, Capsaicin, a TRPV1 agonist, was found to enhance TRPV1-dependent cell proliferation through Akt and ERK pathways." (PMID 34356643, 2021). "The stoichiometric combination of a TRPV1 agonist with a small, positively charged cytotoxic agent constitutes a promising avenue for prostate cancer treatment." (PMID 32545311, 2020). "Looking forward, natural products and drug conjugates can be evaluated for the treatment of prostate cancers with TRPV1 overexpression." (PMID 32545311, 2020). "Expression of functional TRPV1 was also observed in human hyperplastic prostate tissue and prostate cancer cell lines." (PMID 32887220, 2020). "In agreement with channel activity being beneficial for disease outcome, a case report of a prostate cancer patient regularly ingesting capsaicin suggested that TRPV1 activation slows prostate-specific antigen increase." (PMID 32887220, 2020). "Herein, we firstly demonstrated that prostate cancer cell lines co-expressed α1D-AR and TRPV1 proteins and these receptors co-localized mainly in the plasma membrane, perinuclear region and intracellular vesicles." (PMID 25481381, 2014). "TRPV1 is expressed and upregulated in different cancers such as human prostate cancer cells and its activation induces Akt and ERK activation suggesting that TRPV1 activation promotes prostate cancer progression." (PMID 24381558, 2013). "Contradictory results were obtained by using subcutaneous injection of capsazepine (CPZ), a TRPV1 antagonist (5 mg/Kg body weight) in nude mice, that suppressed androgen-independent PC-3 prostate cancer cell growth." (PMID 22523714, 2012). "Similarly, TRPV1 is overexpressed in both human prostate cancer and squamous cell carcinoma of the tongue." (PMID 40243844, 2025). "Elevated TRPV1 expression was shown in breast and prostate cancer." (PMID 35163843, 2022).
prostate carcinoma (continued). "In fact, TRPV1 has been recognized as part of the molecular repertoire of prostate cancer (PC)." (PMID 33803867, 2021). "However, the heterogeneity of breast and prostate cancer cells and possibility of channel desensitization, casts doubts on TRPV1 targeting in malignancies." (PMID 32887220, 2020). "It has been reported that TRPV1 expression increased with increasing tumor grade in prostate cancer biopsies, but it was inversely correlated with tumor stage in bladder cancer suggesting that the relationship between TRPV1 expression and tumor behavior may be tumor-type specific." (PMID 29066974, 2017). "Moreover, alpha1D-AR and TRPV1 are co-expressed in prostate cancer cell lines and specimens." (PMID 25481381, 2014). "Conversely, low-dose TRPV1 activation may stimulate PI3K/AKT signaling and promote proliferation in androgen-sensitive prostate cancer cells." (PMID 41465505, 2025). "The effects of CBD on cell viability werenot blocked by cannabinoid receptor antagonists, a transient receptorpotential vanilloid 1 (TRPV1) channel blocker, or an agonist of theG-protein-coupled receptor GPR55, suggesting that CBD acts independentlyof these targets in prostate cancer cells." (PMID 37703852, 2023). "Conversely, the TRPV1 was highly expressed in prostatic cancer, and the lack of TRPV1 inhibited the spread of prostate cancer cells." (PMID 31183372, 2019). "Expression of 12-lipoxygenase, the enzyme involved in generation of 12(S)-HETE, is correlated with more malignant stages of prostate cancer; 12(S)-HETE is a well-known endo-agonist ligand of TRPV1, shown to increase the firing rate of sensory neurons via activation of the TRPV1 channel opening." (PMID 28640864, 2017). "TRPV1 expression is upregulated in prostate cancer, but it is not the only vanilloid receptor that is related." (PMID 27472308, 2016). "To test these findings, we used prostate cancer cells (PC3), as positive controls expressing TRPV1." (PMID 23468922, 2013). "Previous studies have revealed Trpv1-independent cellular responses to capsaicin; for example, capsaicin (~200 μM)-induced cell growth inhibition was not affected by Trpv1 antagonists in LNCaP and PC-3 prostate cancer cells." (PMID 29339762, 2018).
cardiac hypertrophy (28 papers, 2014 to 2026). "Myocardial hypertrophy with upregulation of TRPV1 expression and loss of cardiac function as well as markers of fibrosis were found to be higher in untreated animals compared to those where TRPV1 was pharmacologically or genetically (TRPV1−/−) unfunctional." (PMID 36277180, 2022). "This suggests that TRPV1 expression is associated with cardiac hypertrophy in this new genetic model of impaired cardiac function caused by overexpression of the cardiac-specific protein phosphatase 2A catalytic subunit." (PMID 34040539, 2021). "Limited studies in literature have investigated the role of TRPV1 in the pathogenesis of myocardial hypertrophy and the underlying molecular mechanisms and the findings are not uniform." (PMID 34040539, 2021). "Interestingly, TRPV1 expression is linked to cardiac hypertrophy, while its knockdown protected heart function in a murine model of hypertrophy." (PMID 38254656, 2023). "In addition, TRPV1 deficiency exacerbates myocardial hypertrophy and impairs diastolic function and myocardial interstitial fiber proliferation in a mouse model of transverse aortic constriction-induced de novo cardiac pressure overload." (PMID 36045746, 2022). "A correlation between TRPV1 and myocardial hypertrophy is known, but the role of TRPV1 in the pathogenesis of myocardial hypertrophy and the underlying molecular mechanisms remain unclear." (PMID 34040539, 2021). "Conceivably, activation of TRPV1 may alleviate cardiometabolic organs dysfunction, including ameliorating atherosclerosis, cardiac hypertrophy, non-alcoholic fatty liver, and stroke risk." (PMID 27120617, 2016). "Therefore, the role of TRPV1 in the molecular mechanism underlying pathological cardiac hypertrophy still remains unclear." (PMID 30881310, 2019). "In models of myocardial hypertrophy induced by pressure overload, TRPV1 expression is significantly upregulated." (PMID 41583526, 2026). "Although current research predominantly focuses on TRPV1's role in pressure overload scenarios, mechanical stress, a major factor in such overload, suggests a potential involvement of TRPV1 in mechanical stress-induced cardiac hypertrophy as well." (PMID 41583526, 2026). "Since its discovery, TRPV1 has been involved in a wide range of physiological functions like inflammation, cancer, neurodegenerative diseases, cardiac hypertrophy, heart failure, and immunity." (PMID 37759544, 2023). "Further, the use of TRPV1 antagonists can prevent or improve myocardial hypertrophy and myocardial fibrosis and reduce the levels of apoptosis markers." (PMID 36045746, 2022). "In a study using TAC to simulate acute pressure overload, the cardiac function of TRPV1-/- mice was improved compared with that of wild type mice, and myocardial hypertrophy, fibrosis, and tissue remodeling were reduced." (PMID 36045746, 2022). "In these studies, TRPV1 was observed to play a beneficial role in the model of pathological cardiac hypertrophy, such as protecting mitochondrial function and reducing anti-inflammatory response." (PMID 34040539, 2021). "This study suggests that the MAPK signalling pathway and intracellular polyamines are important in TRPV1-induced cardiac hypertrophy." (PMID 34040539, 2021). "Many experimental studies have shown that TRPV1 plays a protective or preventive role in the occurrence and development of pathological myocardial hypertrophy." (PMID 34040539, 2021). "In further support of the cardioprotective role for TRPV1, mice fed chow containing the TRPV1 agonist capsaicin experienced less adverse effects of PO, including reduced cardiac hypertrophy and fibrosis, compared with mice fed regular chow." (PMID 33922466, 2021). "Our team plans to conduct more studies in the future to further explore the relationship between TRPV1 and the occurrence and development of pathological cardiac hypertrophy and the internal mechanisms." (PMID 34040539, 2021).